CD8A (CD8 subunit alpha)
Diseases named in the same sentence as CD8A in open-access papers (continued):
Sharing a sentence is not in itself a finding about the gene and the disease.
infection (continued). "The absence of CD11b and F4/80 staining demonstrates that these cells are mostly distinct from classical myeloid-related CD8α− CD11b+ DC present in the spleen of naive mice and CD11b+ inflammatory DC observed during the acute phase of infection in resistant mice." (PMID 26376185, 2015). "Cross-presentation of YopE by CD8α+ DCs may have contributed to the formation of the large ET response during infection with the strain mE." (PMID 26468944, 2015). "For example, only 62 ± 10 CD8α− pDCs reside in lung prior to infection." (PMID 24586061, 2014). "During the PE period, the levels of activated CD4+ and CD8α+ cells in vaccinated pigs were significantly higher than in controls during the first weeks before infection (15-17 weeks); these subsets were mainly constituted of naïve and memory T helper cells able to respond to PCV2." (PMID 24735253, 2014). "CD8α+ and CD8β+ cells were increased in the infected groups throughout the infection experiment; however, the cell counts were significantly higher, for both subpopulations, in the S. Virchow infected group compared to the S. Typhimurium infected group and the uninfected group at 11 DPI (P < 0.036)." (PMID 26664914, 2014). "Consequently, flow cytometry analysis of CD8α+ cells in liver and spleen at day 5 post-infection revealed a decrease in the number of CD8α+ cells in the spleen and an increased population in the liver." (PMID 25338079, 2014). "To investigate whether microbial glycolipid antigen presentation also required CD8α+ DCs in the setting of infection, we compared the lung burdens of Batf3−/−and WT mice after intranasal infection with S. pneumoniae." (PMID 24412610, 2014). "Furthermore, it showed that the same DC subset as required for priming CD8+ T cell immunity to blood-stage infection, i.e the CD8α+ DC, was responsible for inducing CD8+ T cell responses to the liver-stage parasites." (PMID 24854165, 2014). "NK cells activate CD8α+ DCs that prime CD8+ αβ T cells after infection with P. berghei ANKA." (PMID 24009610, 2013). "Interestingly, infection-induced enhancement of Cd8α and granzyme A (gzma) expression was most prominent in the proximal small intestinal tissue with only minor differences observed in the distal part of the small intestine." (PMID 22570612, 2012). "Pathogen sensing may not be the only problem in aged mice, and it is likely that efficient delivery of Lm into the CD8α+ DC subset as a result of age-related changes within the splenic environment may also compromise the establishment of infection." (PMID 22862959, 2012). "Interestingly, when we evaluated the histograms for costimulatory expression, it was clear that adult CD8α+ DC appeared to almost uniformly upregulate these costimulatory molecules for the first 3 days post-infection." (PMID 22862959, 2012). "Depletion of CD8a+ T cells in these mice leads to lethal maEBOV infection." (PMID 21994766, 2011). "Interestingly, despite the deficiency in the CD8α chain in CD8α−/− mice, we were able to detect an increase in CD8β mRNA production at later stages of infection versus the level in uninfected CD8α−/− mice." (PMID 21629771, 2011). "We find that CD8α+ DCs are the most susceptible to infection while plasmacytoid DCs are not infected." (PMID 21559416, 2011). "Upon infection, CD11b+ DCs primarily secrete low levels of TNFα while CD8α+ DCs secrete IL-12 p70." (PMID 21559416, 2011). "Furthermore, the proportion of CD8α+ γδ T cells expressing IFN-γ is elevated during early cytolytic infection in chickens superinfected with RB-1B after vaccination, highlighting their pivotal role in initiating a cytokine-mediated antiviral response during innate immunity." (PMID 40733525, 2025). "The protein expression of seven proteins (CD8A, ST1A1, AXIN1, FGF-5, MMP-10, HGF, SIRT2) was significantly decreased and the protein expression of two proteins (MMP-1, TNFRSF9) was significantly increased in caspase-1-deficient cells compared to Cas9 cells following HK1651 infection." (PMID 40137780, 2025).
infection (continued). "Importantly, we could retrieve these antiviral CD8+ T cells in the lung parenchyma of mice treated with WT IL-1β or CD8α ALN-1 more than 50 days after the initial infection, illustrating the longevity of these cells." (PMID 32714571, 2020). "As there were apparent differences in OT1 T cell numbers in spleen and LN between anti-CD8α and –β treated mice, we next stained for select molecules involved in localization that are known to vary in expression across T cell differentiation states 7 days after immunization or infection." (PMID 30735510, 2019). "As MVA infection modulates multiple innate cell subsets such as cDCs, plasmacytoid DCs, macrophages, and NK cells, additional studies would be needed to better address the specific contribution of antigen cross-presenting CD8α+ cDCs in the context of generation of antitumor immune responses." (PMID 31695037, 2019). "However, as mice lacking either IFN-γ or IL-12p40 are highly susceptible to infection with Mtb, we considered it likely that the IL-12 producing capabilities of langerin+ CD8α+ DCs would contribute to control of a systemic mycobacterial infection." (PMID 29867941, 2018). "We suspect that accumulation of CD8α+ DCs in the liver could be the outcome of enhanced migration of these cells which is critically dependent on the availability of specific chemokines required for the migration of DCs to the site of infection." (PMID 29472929, 2018). "Therefore, we investigated infection in CD8α knockout mice to determine whether these cells played any role in virus clearance or persistence." (PMID 29783708, 2018). "This suggests the role of langerin+ CD8α+ DCs in antimycobacterial control may be of particular significance in the first week after infection, and the importance of this early effect on the ensuing immune response is maintained throughout the bacterial proliferation phase." (PMID 29867941, 2018). "Furthermore, deletion of the CD8a−/− gene leads to 100% death after infection." (PMID 28649242, 2017). "However, to confirm this conclusion an experiment that depletes both B cells and CD8a+ lymphocytes prior to infection could be conducted." (PMID 21747924, 2011). "Therefore, targeting of CD8α+ DCs by Ye may result in immune evasion of the pathogen as infection control requires CD4+ Th1 host responses." (PMID 21124820, 2010). "In mice, splenic CD8α+ and CD8α− DC subsets have been extensively studied and some functional differences between the two subsets have been reported in several model systems including infections, although some studies showed overlapping functions of the two subsets." (PMID 20174628, 2010). "γδ-TCR+ cells are considered rapid responders to infection with multiple protective roles and can be separated into naïve- (CD2−CD8α−, cluster 5), activated- (CD2+CD8α−, cluster 4), and effector- (CD2+CD8α+, cluster 8) γδ-TCR+ cells." (PMID 41510007, 2025). "While the depleted groups showed minimal inflammation at 4 wk after infection, most CD4- and CD8α-depleted macaques had high lung FDG activity by 8 wk after Mtb, with significantly higher total lung FDG activity compared with IgG/saline-vaccinated animals." (PMID 39912921, 2025). "Conversely, a decrease in blood CD4+ Tregs, which includes both CD4+CD8α+ and CD4+CD8α− Tregs, was found in infections with CADC_HN09." (PMID 41510007, 2025). "The number of mRNA copies of the B-cell-related genes Pax5, CD5, and CD19; T-cell-related gene CD8A; and MHC-related genes CIITA, HLA-DQ1, HLA-DR, and HLA-DO were significantly decreased in patients with infections." (PMID 40185975, 2025). "Eight days post-infection (dpi) with LCMV-Armstrong, the proportions, and numbers of antigen-experienced Tet1/3cDKO CD8 T cells, as assessed by low CD8a and positive CD11a expression, were modestly increased compared to WT littermate controls." (PMID 40175595, 2025).
infection (continued). "Tregs, which have been described to contribute to the control of tissue damage in infection, were also investigated in infections with Armenia2008, where CD4+CD8α− Tregs were upregulated at 7 dpi in the blood, spleen, and GHLN." (PMID 41510007, 2025). "Upon infection, signaling of BECs via MHC-related genes to Cd8a and Killer-like lectin receptors was found by MultiNicheNet analysis, indicative of antigen presentation by BECs in MHC-I to the Teff cells." (PMID 38236930, 2024). "CD86 expression was increased in CD8α- and pDCs in both PEP-WT and PEP-619WW mice following infection." (PMID 38512979, 2024). "Cytotoxic T cells are believed to be involved in virus clearance, and increased expression of CD8α and GZMa has been found to correlate with decreasing PRV-1 RNA levels in the later stage of infection." (PMID 36694262, 2023). "Our data strongly suggest that CTL responses correlate with protection against PRRSV-1 transplacental infection, being executed by CD4 T cells (IFN-γ related) and/or CD4/CD8α DN T cells (TNF-α related)." (PMID 36798517, 2022). "Our data strongly suggest that CTL responses are correlated with the protection against PRRSV-1 transplacental infection, being executed by CD4 T cells or CD4/CD8α DN cells." (PMID 36798517, 2022). "After infection with and clearance of the low virulent OURT88/3, surviving animals were depleted of CD8α+ lymphocytes with specific antibodies (clones 76-2-11 and 11/295/33)." (PMID 35215216, 2022). "To determine if infection with the very virulent MDV strain RB1B also induced expansion of γδ T cells and CD8α+ T cells in chicken, we examined the dynamic changes of these populations in the spleen and lung of RB1B-infected birds." (PMID 33659011, 2021). "Here, we identified a critical role for C5a/C5aR1 axis activation in CD8α+ splenic DCs resulting in IL-12 and subsequent IFN-γ production from NK cells during the first week after infection, eventually controlling parasite proliferation and persistence." (PMID 32733463, 2020). "Cr infection induced up-regulation of CD8+ T cell markers such as Cd8a, Cd8b, and FasL, suggesting involvement of CD8-mediated pathways in Cr infection." (PMID 33076301, 2020). "The L. donovani infection in BALB/c mice promotes IL-27 expression by splenic CD8α+ and CD4+ DCs on days 1, 14, and 28 post-infection." (PMID 32849534, 2020). "The recruitment of CD4+ or CD8α+ T cells to the brain was unchanged in T. gondii-infected and co-infected mice (MANOVA with cell type as dependent variable and infection status as fixed factor: F2, 7 = 2.65, Wilks’ Λ = 0.569, p = 0.139)." (PMID 31352901, 2019). "To test this possibility, we first depleted CD8+ T cells using CD8α-specific antibodies in B6 and CD169−/− mice challenged subcutaneously with FVC and monitored infection in the spleen." (PMID 30595553, 2019). "The expression of CD8a, CD74, and BCL6, which are regulators of MHC class II molecules and B-cell differentiation, was downregulated during early vvIBDV infection." (PMID 28086922, 2017). "Infection with either strain increased expression of ISGs (GBP1, IFIT1, IRF7) and reduced expression of lymphocyte related genes (CD3D, CD8A, ZAP70)." (PMID 28852031, 2017). "The frequency of CD11c+ T cells expressing CD8α in blood was similar before and after infection, while NK1.1 expression increased markedly following infection." (PMID 27119555, 2016). "To explore the antigen location in different tissues during infection, we primarily determined the viruses, CD4+ cell and CD8α+ cell locations by IHC staining assays." (PMID 27150912, 2016). "More recently, increased frequencies of cytolytic T cells (CTLs), CD4+CD8α+ T cells and regulatory T cells have been reported in lung tissue and bronchoalveolar lavage fluid of H1N1-infected pigs six days post infection." (PMID 25971313, 2015).
infection (continued). "We did observe proliferation of OT-1 in the D-LN after infection with NP-S-EGFP, but the proliferation observed was equivalent in wild-type and Batf3-/- mice, indicating that CD8α + DC are dispensable for initiation of an OVA-specific TCD8+ response." (PMID 26107264, 2015). "After S. Virchow infection, numbers of CD4+, CD8α+, and CD8β+ cells had increased in the ileum by five DPI, indicating a T helper and a cytotoxic T cell response had occurred." (PMID 26664914, 2014). "While the percentage of the CD2−CD8α− phenotype increased significantly in INOC gilts after infection, the percentages of both CD2−CD8α+ and CD2+CD8α+ γδ T cells were significantly decreased in INOC gilts." (PMID 25497114, 2014). "Because of the previous transcriptional results obtained, we analyzed the percentage of IgM+, IgT+, IgD+, CD8α+ and MHC-II+ cells at day 5 post-infection in both control and infected animals." (PMID 25333488, 2014). "Remarkably, this disparate response also extended to DCs isolated from LNs draining the site of infection with CD103+, CD11b+, CD8α+ and Langerhans cell-containing CD103−CD11b−CD8α− subsets inducing IFN-γ production by gDT-II, but not gBT-I TEFF cells." (PMID 25121482, 2014). "B cells, T helper cells and CTLs with an effector or memory phenotype (CD21−, CD8α+, SLA-DR+, respectively) were less affected by the drop in absolute counts after PRRSv infection." (PMID 25497114, 2014). "Statistical analysis showed an overall strong correlation of Eomes expression with CD8α and granzyme A, as well as between granzyme A and IFN-γ expressions post infection." (PMID 23409078, 2013). "We observed that among CD11c+MHCII+ cells at the peak of the infection, CD103+ DC numbers had increased substantially in the MLN, with CD103+CD8α− DC being the predominant subset over the CD103+CD8α+ DC subset." (PMID 24367259, 2013). "At the terminal phase of infection (phase of neurological signs of the disease), the levels of all chemokines/cytokines tested were analogous in TBEV-infected CD8α−/− mice and in C57Bl/6 mice on day 14 p.i.." (PMID 21629771, 2011). "Upon infection of mice with E. coli or treatment with LPS, the number of CD4+ and CD8α+ DCs was markedly reduced 48 hours later, a result of TLR4-TRIF signaling induced apoptosis." (PMID 21124820, 2010). "The transcript abundance of costimulatory molecules (such as CD86, ICOS), CAMs, and TCRs/CD3 complex as well as co-receptor molecules (such as CD8A, CD8B) was remarkably increased after infection with N-PRRSV." (PMID 20614006, 2010). "Additionally, the CD3+CD4+ T lymphocyte subset was consistently higher in WCCs, both prior to and after infection, whereas RWFCs displayed a higher quantity of CD3+CD8α+ T lymphocytes." (PMID 40941329, 2025). "CD4+/CD8α- helper T cells did not vary significantly throughout infection, while CD4-/CD8α+ cytotoxic T lymphocytes (CTLs) decreased from 1 DPC to 5 DPC." (PMID 41156603, 2025). "Similar results were seen in splenic CD8α− cDCs, which are likely type 2 conventional dendritic cells (cDC2s), though there was a decrease in CD86 expression in PEP-null and PEP-R619W splenic CD8α− cDCs compared to PEP-WT post-infection." (PMID 40791464, 2025). "We then performed a similar analysis of various organs (liver, spleen and peripheral LNs) of C57BL/6 (B6) mice at day 5 after infection with Plasmodium berghei ANKA sporozoites and, similarly, detected three subsets of γδ T cells based on CD8α versus CD8β expression." (PMID 38802512, 2024). "Neither the CD8α nor the IL-1α treated mice lost weight or had changes in food consumption following infection." (PMID 38382577, 2024). "Cluster 3, which identified genes upregulated at day 7 post-infection, was highly enriched for T cell responsive genes, including those involved in T cell activation, lymphocyte proliferation, and TCR signaling, e.g. CD3D/E/G, CD8A/B, CD28, CD40LG, and GATA3." (PMID 38950078, 2024).
infection (continued). "Infection with C. perfringens also altered the frequency of CD4+ and CD8α + αβ T cells." (PMID 38164397, 2023). "The expression of adaptive immune response genes, mIgM, CD4 and CD8a was significantly upregulated in heart tissues of PRV-1 infected fish, indicating both B/T cell mediated immune responses and influx of B and T cells to the site of infection/inflammation." (PMID 37644605, 2023). "Later during infection, non-infected CD8α+ XCR1+ cDCs loaded viral antigens through cross-presentation and presented antigens to both T cell subsets through MHC-1 and MHC-II." (PMID 36936763, 2023). "During infection with highly virulent Armenia2007, the response was dominated by DP T cells in both subspecies with no changes of CD8α+ CTLs until the end of the study seven dpi." (PMID 35215216, 2022). "The same pattern was seen in both groups of sows (without transplacental infection: 40.8 ± 13.3% in CD4 SP and 44.3 ± 20.0% in CD4/CD8α DP; with transplacental infection 41.5 ± 15.9% and 47.0 ± 11.8% respectively; non-significant)." (PMID 36798517, 2022). "Recently, populations of CD4+, CD8α+, and non-CD4+CD8α+ T cells in the liver and spleen of turkeys were induced following administration of attenuated H. meleagridis as a putative vaccine and subsequent virulent infection." (PMID 35601402, 2022). "The expansion of these cells was CVI988-specific as infection with very virulent MDV RB1B did not elicit expansion of either γδ or CD8α+ T cells." (PMID 33659011, 2021). "Similarly, in chickens, another γδ-high species such as the pig, increased numbers of CD8α+high γδ T cells were observed in blood, spleen and cecum after STM infection along with enhanced expression levels of IFN-γ mRNA in these cells." (PMID 34451970, 2021). "Instead, blockade of IFNβ but not IFNα improved splenic architecture, decreased infection of CD8α− DC, and enhanced antiviral T cell responses that led to clearance of persistent virus, mimicking many of the effects seen with IFNAR1 blockade." (PMID 33408718, 2020). "As previously published, N-803 resulted in robust and persistent virus reactivation in CD8α-depleted, ART-treated, SIVmac239-infected macaques, and these results were recapitulated, albeit to a lesser degree, in an SHIVSF162P3 model of infection as well as in HIV-infected humanized mice." (PMID 32669328, 2020). "However, Cr-infection significantly decreased expression of B- and T-cell markers (CD19, CD45R; CD4, CD8a) in the spleen." (PMID 33076301, 2020). "In contrast, our previous findings demonstrate that DC depletion results in an approximately 5-fold reduction of latent virus and significant reduction in viral reactivation, suggesting that CD8α+ DCs contribute to increased latency but not primary infection." (PMID 30998796, 2019). "Infection with both mild and HP-PRRSV strains also results in a decrease in CD8α+ γ/δ T cells." (PMID 31156633, 2019). "To determine if splenic langerin+ CD8α+ DCs were required for control of systemic BCG infection, we used lang-DTREGFP mice (referred to as Lang-DTR mice), which allowed depletion of langerin-expressing cells with DT during the course of infection." (PMID 29867941, 2018). "After resolution of the acute infection, CD8α knockout mice had no detectable infectious virus showing that these cells are not required to maintain levels of virus infectivity undetectable." (PMID 29783708, 2018). "We report herein that during intravenous Mycobacterium bovis bacille Calmette–Guerin (BCG) infection, the depletion of langerin+ CD8α+ DCs led to a diminished immune response, with decreased serum IL-12p40 and delayed CD8+ T cell activation, proliferation, and IFN-γ production during infection." (PMID 29867941, 2018). "In the absence of Batf3-dependent CD8α+ DC, Lm was unable to establish a productive infection in the T cell zone as they were confined to the marginal zone and rapidly cleared by macrophages." (PMID 29914156, 2018).